NPS (neuropeptide S)
Description:
Ligand for NPSR1. Binds to its receptor with nanomolar affinity and initiates a G(q)/GNAQ-dependent phospholipase C-activating signaling pathway. This results in Ca(2+) mobilization from intracellular stores and increased intracellular Ca(2+) levels. In addition to this pathway, NPS binding to its receptor activates cAMP/PKA signal transduction. Finally, both pathways converge to activate ERK1/ERK2 phosphorylation and signaling cascade. Modulates arousal and anxiety. May play an important anorexigenic role (By similarity).
Tractability: Antibody: its Gene Ontology location is reachable by antibodies, with high confidence; UniProt places it where antibodies can reach, with medium confidence; UniProt predicts a signal peptide or a membrane-spanning region.
Target class: Secreted protein
Gene: Protein-coding gene on chromosome 10 (127,549,309 to 127,553,540, forward strand). Ensembl gene ENSG00000214285.
Subcellular location: Secreted
Pathways (Reactome):
Signal Transduction: G alpha (q) signalling events; G alpha (s) signalling events; Peptide ligand-binding receptors
Gene Ontology:
Molecular function: neuropeptide activity
Biological process: phospholipase C-activating G protein-coupled receptor signaling pathway; positive regulation of cAMP/PKA signal transduction; positive regulation of ERK1 and ERK2 cascade; positive regulation of action potential; positive regulation of synaptic transmission, GABAergic; positive regulation of synaptic transmission, glutamatergic; neuropeptide signaling pathway; positive regulation of circadian sleep/wake cycle, wakefulness
Cellular component: extracellular region
Genetic constraint (gnomAD): Loss-of-function variants: 0 observed, 1.14 expected, observed/expected ratio (o/e) 0, 90% interval 0 to 1.68. That is too few expected variants to judge how well the gene tolerates losing a copy. Missense variants: 48 observed, 37.31 expected, observed/expected ratio (o/e) 1.29, 90% interval 1.02 to 1.63. Synonymous variants: 14 observed, 11.29 expected, observed/expected ratio (o/e) 1.24, 90% interval 0.81 to 1.82.
Homologues: Orthologues: chimpanzee NPS (96% identical), macaque NPS (93% identical), dog NPS (78% identical), pig NPS (74% identical), rabbit NPS (74% identical), mouse Nps (73% identical), rat Nps (73% identical), guinea pig NPS (66% identical), tropical clawed frog NPS (60% identical).
Diseases named in the same sentence as NPS in open-access papers:
NPS is named in the same sentence as 37 diseases in open-access papers, as found by Europe PMC text mining. Sharing a sentence is not in itself a finding about the gene and the disease. The quoted sentences say what the papers report.
Anxiety (25 papers, 2008 to 2025). Intense feelings of nervousness, tension, or panic often arise in response to interpersonal stresses. "Neuropeptide S is a neurotransmitter, it operates as a neuromodulator, especially in the onset of anxiety and arousal." (PMID 39025836, 2024). "Neuropeptide S (NPS) is a factor associated with the central regulation of body weight, stress, anxiety, learning, memory consolidation, wakefulness–sleep cycle, and anti-inflammatory and neuroplastic effects." (PMID 35741653, 2022). "Neuropeptide S at 1 nmol icv decreased the sleep disorder-induced anxiety-like action and inhibited electroencephalographic theta band frequency." (PMID 34069327, 2021). "The neuropeptide S/neuropeptide S receptor (NPS/NPSR) system is involved in the regulation of the anxiety induced by chronic inflammation." (PMID 34408622, 2021). "NPSR1 is a member of the G-protein-coupled receptor binding neuropeptide S (NPS) and plays a role in arousal and anxiety-like behaviors." (PMID 29770110, 2018). "Neuropeptide S (NPS) increasingly emerges as a potential novel treatment option for anxiety diseases like panic and posttraumatic stress disorder." (PMID 23555930, 2013). "Neuropeptide S (NPS) is an endogenous peptide that regulates various physiological functions, such as immune functions, anxiety-like behaviors, learning and memory, the sleep–wake rhythm, ingestion, energy balance, and drug addiction." (PMID 34069327, 2021). "The neuropeptide S (NPS) and its receptor (NPSR1) have been extensively studied over the last two decades for their roles in locomotion, arousal/wakefulness and anxiety-related and fear-related behaviours in rodents." (PMID 34451877, 2021). "Neuropeptide S (NPS) is a peptide neurotransmitter that in animal studies promotes wakefulness and arousal with simultaneous anxiety reduction, in some inconsistency with results in humans." (PMID 34070724, 2021). "Neuropeptide S (NPS) and NPS receptors (NPSR) are reported as a novel endogenous arousal and anxiolytic system, but it is unclear yet whether this system is involved in anxiety-like behavior and sleep caused by sleep deprivation, and how it plays anxiolytic effect underlying the comorbid condition." (PMID 29559896, 2018). "The Neuropeptide S system, consisting of the 20-amino acid peptide neuropeptide S (NPS) and its G-protein coupled receptor (NPSR), modulates arousal, wakefulness, anxiety, and fear-extinction in mice." (PMID 27013974, 2016). "We have previously investigated modulatory effects of neuropeptide S (NPS), a potential novel treatment option for pathological anxiety, in the vHPC." (PMID 25830625, 2015). "Neuropeptide S (NPS), a brain peptide hormone highly conserved in vertebrates, has diverse physiological effects on anxiety, fear, hyperactivity, food intake, and sleeping time through its cognate receptor-NPSR." (PMID 24386135, 2013). "The recently discovered neuropeptide S (NPS) and its receptor (NPSR) also seem to impact arousal, fear, and anxiety responses." (PMID 23630477, 2013). "The serotonin (5-HT) and neuropeptide S (NPS) systems are discussed as important genetic modulators of fear and sustained anxiety contributing to the etiology of anxiety disorders." (PMID 23630477, 2013). "neuropeptide S (NPS) and its receptor NPSR1 act along the hypothalamic-pituitary-adrenal axis to modulate anxiety, fear responses, nociception and inflammation." (PMID 22216302, 2011). "Neuropeptide S (NPS) and its receptor are thought to define a set of specific brain circuits involved in fear and anxiety." (PMID 18628994, 2008). "A large literature has shown that various neuropeptides, including corticotropin-releasing factor (CRF), cholecystokinin (CCK), arginine vasopressin (AVP), oxytocin, orexin, neuropeptide Y (NPY), neuropeptide S (NPS), galanin, and neurokinins, such as substance P, affect anxiety-related behaviors." (PMID 36623804, 2023).
Anxiety (continued). "Neuropeptide S promotes GABA release from interneuron to amygdala at the cellular level; therefore, changes in the GABAergic neuronal activity due to NPS resulted in a change in anxiety-like behavior." (PMID 34069327, 2021). "The neuropeptide S (NPS) system was discovered as a novel neurotransmitter system a decade ago and has since been identified as a key player in the modulation of fear and anxiety." (PMID 25714705, 2015).
anxiety disorder (4 papers, 2013 to 2024). A category of psychiatric disorders which are characterized by anxious feelings or fear often accompanied by physical symptoms associated with anxiety. "Given the relevance of the neuropeptide S system in fear processing, we investigated a possible association of the functional NPSR1 rs324981 gene variant with neural correlates of sustained, phasic fear, and symptom reduction in a prototypical anxiety disorder not investigated yet." (PMID 39167471, 2024).
depression (4 papers, 2015 to 2022). "The present study proposes to investigate the effect of neuropeptide–S (NPS) on cognitive functions and depression-like behavior of MPTP-induced experimental model of Parkinson’s disease (PD)." (PMID 34289654, 2021).
schizophrenia (4 papers, 2015 to 2022). A major psychotic disorder characterized by abnormalities in the perception or expression of reality. "As outlined in S11 Table, seven of these genes have, to varying degrees, plausible links to cognition (i.e. DGKB, NPS, VPS13B, RBM20, ABHD4, ESRRB, and DOPEY2), with some active in systems implicated in schizophrenia pathology (NPS, DGKB, ABHD4, ESRRB)." (PMID 25860228, 2015). "The neuropeptide S (NPS) system has received considerable attention as either a genetic risk factor or potential therapeutic target for several psychiatric disorders, including anxiety and schizophrenia." (PMID 34065431, 2021).
alcohol use disorder (3 papers, 2018 to 2024). "In addition, neuropeptide S seems to play a role in the pathogenesis of alcohol use disorder and relapse risk after alcohol detoxification." (PMID 36263121, 2022). "Due to still limited data, no firm conclusions can be drawn at the moment, but further investigation of neuropeptide S and NPSR genetic variants in relation to alcohol use disorder appears justified." (PMID 36263121, 2022). "Taken together, these results suggest that the neuropeptide S regulation system and its receptors may be of interest in the treatment of alcohol use disorder." (PMID 36263121, 2022). "The roles of neuropeptide S (NPS) and neuropeptide Y (NPY) in alcohol use disorder are reported by Rodriguz and Covenas." (PMID 34466439, 2018).
asthma (3 papers, 2012 to 2017). "In conclusion, NPS variants modify asthma risk and should be considered in genetic association studies of NPSR1 with asthma and other complex diseases." (PMID 28463995, 2017). "Another NPS SNP (rs10830123) showed borderline association with asthma, and formed a protective haplotype with NPS rs1931704 and NPS rs4751440." (PMID 28463995, 2017).
mental disorder (3 papers, 2016 to 2022). A disease that has its basis in the disruption of mental process. "In turn, alterations of NPSR1 signaling efficacy by nonsynonymous mutations in the NPSR1 or the NPS gene might consequently alter behavior and the risk for the development of psychiatric disorders." (PMID 34072275, 2021). "Each article with the following key words likes neuropeptide-S, mental disorders, stress was included in the analysis." (PMID 35558538, 2022). "The publication contains thematic subsections analyzing the impact of stress on the body's reactions, the level of neuropeptide-S and mental disorders." (PMID 35558538, 2022). "Furthermore, it was found that hub proteins, such as COMT, POMC, NPS and BDNF, might be the potential targets for mental disorders therapy." (PMID 27917343, 2016).
Arthritis (1 paper, 2014). Inflammation of a joint. "The key novelty of this is study is the finding that nasal application of recently discovered neuropeptide S (NPS) can inhibit pain behaviors in an arthritis model." (PMID 24884567, 2014).
panic disorder (1 paper, 2024). An anxiety disorder characterized by multiple unexpected panic attacks with persistent concern of recurring attacks. "The neuropeptide S gene (NPS) has been linked to anxiety-related disorders, fear behavior, and panic disorder in humans." (PMID 39766878, 2024).
paraganglioma (1 paper, 2014). A benign or malignant neoplasm arising from paraganglia located along the sympathetic or parasympathetic nerves. "Pheochromocytomas of the adrenal medulla showed no or only very low immunoreactivity for NPSR1 and NPS whereas extra-adrenal sympathetic paragangliomas showed stronger reactivity for the antigens." (PMID 24915894, 2014).
cancer (3 papers, 2021 to 2023). A tumor composed of atypical neoplastic, often pleomorphic cells that invade other tissues. "The non-constitutive proteasomes (intPs and iPs, together nPs) have been shown to modulate different aspects of cellular and organ homeostasis from gene expression to the immune reactions and have attracted much attention because of their role in cancer, autoimmune and neurodegenerative diseases." (PMID 34831272, 2021).
NPS also shares sentences with these, for which no sentence is quoted: Alzheimer disease (2 papers); Cognitive impairment (2); Obesity (2); posttraumatic stress disorder (2); acne vulgaris (1); Anorexia (1); childhood asthma (1); cicatricial pemphigoid (1); hypothyroidism (1); Immune Disorders (1); infectious disease (1); intestinal inflammation (1); magnesium deficiency (1); myocardial infarction (1); nail-patella syndrome (1); neurodegenerative disease (1); osteoarthritis (1); parasite infection (1); Parkinson's (1); periodontitis (1); pheochromocytoma (1); Proteinopathies (1); Pruritus (1); skin disorder (1); stress cardiomyopathy (1); stress-related disorder (1).